INS (insulin)
Diseases named in the same sentence as INS in open-access papers (continued):
Sharing a sentence is not in itself a finding about the gene and the disease.
diabetes (continued). "Therefore, we repeated the analysis separating patients with diabetes into those taking and not taking insulin, a marker of diabetes severity." (PMID 33648518, 2021). "However, Sahebjami and Denholm reported that lack of insulin in diabetes did not retard lung growth, although it reduced body weight." (PMID 33661932, 2021). "However, it has not gained much attention, unlike insulin, which has a therapeutic effect for diabetes." (PMID 34199839, 2021). "In patients without a family history of diabetes, the Insulinogenic index which indicated an early phase of insulin secretion continued to worsen throughout 2 years of lifestyle intervention; however, insulin resistance did not change significantly in the DMFH(-) group." (PMID 33490287, 2021). "Diabetes: S/V is beneficial irrespective of glycemic status, with a reduced incidence of diabetes and a low percentage of subjects requiring oral anti-hyperglycemic therapy or new insulin use." (PMID 34497530, 2021). "Type 2 diabetes mellitus, where body cells could not utilize or produce insulin, is considered the most typical type as around 90% of the globally identified diabetic population." (PMID 35047273, 2021). "Improvement in insulin sensitivity and improvement in beta cell function were noted following Roux-en-Y gastric bypass surgery in severely obese adolescents and young adults without diabetes." (PMID 33435250, 2021). "In addition, we found that the levels of hsa_circ_0054633 in the serum of patients with IR who were treated with insulin were significantly lower than normal group and diabetes without insulin treatment group (p = 0.0002 and p < 0.0001)." (PMID 34272768, 2021). "The differential inflammatory profile and insulin signaling in the hypothalamus of non-diabetic (ND) and diabetic (D) IRS2−/− mice might be implicated in the onset of diabetes." (PMID 34440853, 2021). "Fourth, we did not assess the type and/or severity of diabetes, as well as therapies (insulin or noninsulin‐based therapies), which may influence glycemic control and AF outcomes." (PMID 33539595, 2021). "Diabetes mellitus (DM), due to insulinopenia secondary to degeneration of β-cell in absence of autoimmunity, is an invariable finding that occurs as the first manifestation, has a non-autoimmune origin, and is insulin requiring." (PMID 34831749, 2021). "To explore which has more effects on the offspring health of diabetes, uterine environment or oocytes, we generated type 2 diabetes mouse model by feeding high fat diet combined with STZ, a diabetagen which is especially toxic to pancreatic islet insulin-producing β-cells, injection at a low dose." (PMID 34381787, 2021). "Even for insulin, it is not a cure for diabetes; it is just a treatment." (PMID 34221067, 2021). "Peripheral insulin administration, a therapy used in the case of patients with diabetes, may induce hypoglycemia in AD patients who do not have diabetes; in addition, this treatment may be ineffective as insulin transport across the BBB is impaired." (PMID 34576151, 2021). "As research progressed, researchers found that the effect of MSCs on diabetes was not just mediated by the secretion of insulin; most MSCs could ameliorate IR by their anti-inflammatory potential." (PMID 34135959, 2021). "Because associations were maintained with mutual adjustment for other diabetes medications, it is also plausible that any potential benefit may be specific to metformin rather than to general effects on glycemic control or insulin sensitivity." (PMID 33637087, 2021). "For example, a previous study indicated that the use of insulin for downregulating blood glucose failed to recover the advantages of SPostC, and it may be due to the diabetes-induced inhibition of the PI3K signaling." (PMID 33986917, 2021).
diabetes (continued). "The absence of first-phase insulin reactions to intravenous glucose has long been considered an initial sign of β cell dysfunction and has some anticipative importance for the subsequent development and progression of diabetes." (PMID 34203830, 2021). "In one such assessment, mice with STZ-induced diabetes given root extracts of A. carambola (REAC at daily doses of 150, 300, 600, and 1,200 mg/kg for 21 days) orally had significantly decreased blood glucose, TC, TGs, and FFAs levels and elevated insulin content in their serum." (PMID 34475822, 2021). "However, little is known about the usefulness of machine learning approaches in the decision-making process for decisions such as insulin initiation by diabetes specialists for which no absolute standards exist in clinical settings." (PMID 33502325, 2021). "Our data did not necessarily include all the diabetes medicines used by diabetic patients because some might receive these medicines, especially insulin, through other sources such as humanitarian organizations." (PMID 34645430, 2021). "The much higher proportion of people discussing someone known to them with diabetes may be because of the large scale concern for people with diabetes not being able to afford their insulin." (PMID 33496671, 2021). "This might be due to diabetes if the patient produces little or no insulin, or if the body cannot use the insulin, the sugar remains in the bloodstream instead of going into the cells." (PMID 34484816, 2021). "In addition, the study included only people using insulin and it gave no comparison to other diabetes treatments." (PMID 33407924, 2021). "Type 2 diabetes mellitus (T2DM) is a metabolic disease characterized by fasting and postprandial hyperglycemia and is due to a progressive deficit of insulin secretion that is initiated after a process of insulin resistance; it affects 415 million people worldwide." (PMID 33809864, 2021). "Without β-cell dysfunction, reduced insulin sensitivity alone will not progress to diabetes." (PMID 34579016, 2021). "More importantly, after the onset of obesity and type 2 diabetes mellitus (T2DM), oral treatment with GABA inhibited the continual HFD-induced gain in body weights, reduced the concentrations of fasting blood glucose, and improved glucose tolerance and insulin sensitivity in mice." (PMID 33986956, 2021). "Not having housing also means not having a secure place to store diabetes testing supplies such as glucometers or medications and insulin, and there is a fear that they may be stolen in a communal living arrangement such as an emergency shelter." (PMID 34243783, 2021). "Lower fasting insulin levels were found in healthy women without diabetes with higher Mg intakes." (PMID 33573164, 2021). "Without insulin treatment BB-rats die within 5 and 10 days after manifestation of diabetes." (PMID 33557206, 2021). "Indeed, pulsatile insulin levels in circulating blood of mouse models of diabetes and patients with diabetes, pre-diabetes, and non-diabetic family members of diabetic patients are often disrupted." (PMID 34231467, 2021). "Even though this study does not have baseline fasting plasma glucose, hemoglobinA1c or duration of diabetes to indicate the severity of disease, small amount of insulin use could roughly tell that overall subjects were not poorly controlled diabetes." (PMID 33419413, 2021). "Consequently, in diabetes, insulin insufficiency or insulin sensitivity affects the endocrine route (negative feedback loop), resulting in reduced male reproductive function as a result." (PMID 35054403, 2021). "For type 1 diabetes, many countries do not necessarily provide full coverage for insulin and diabetes supplies within the context of UHC; should these be provided in a comprehensive way, this could have an impact on mortality." (PMID 33483763, 2021).
diabetes (continued). "Substance use disorders may lead to “chronic relapsing just like diabetes and hypertension” (P11).“No more insulin for you is not an option offered to diabetics after eating sweets and reaching high blood sugar levels” (P11)." (PMID 33691677, 2021). "HIF1, once activated, may promote tumorigenic activities leading to the initiation and progression of breast cancer in subjects with diabetes, hence potentiating the role of HIF1-insulin axis in T2DM-BC crosstalk, since, both T2DM and breast cancer are characterized by hypoxia state." (PMID 34225729, 2021). "Patients with type 1 diabetes mellitus (T1DM) or latent autoimmune diabetes of the adult (LADA) using a multiple daily injection (MDI) regimen with carbohydrate counting (n = 25, Subgroup B) or fixed insulin dose (n = 25, Subgroup C) were allocated to use the application (app) for 12 weeks." (PMID 33905630, 2021). "The insulin-independent hypoglycemic mechanism indicates that theoretically, SGLT2 inhibitors might be effective in patients with any stage of diabetes and particularly effective in those with severe insulin resistance and receiving high-dosage insulin therapy." (PMID 32351447, 2020). "However, there are no restrictions on adding other pieces of diabetes technology including insulin pumps or hybrid closed-loop systems." (PMID 32733375, 2020). "Indeed, the prevalence of cognitive deficits in PD patients with diabetes is higher than in those without diabetes, and hippocampal neurons are particularly sensitive to alterations to insulin." (PMID 31963327, 2020). "Doubt over the long-term health benefit of stimulating insulin release per se as a route to reducing PPG is indicated by data from Nateglinide, a drug stimulating insulin release, that was found ineffective in reducing the transition from pre-diabetes to diabetes." (PMID 32647531, 2020). "Although insulin resistance or diabetes enhances PD-related pathogeneses in in vivo and in vitro neuronal models, biological evidence in human studies is lacking and the functional assessment of insulin signaling pathway in PD patients’ neurons is challenging." (PMID 33344443, 2020). "Type 1 diabetes (insulin-dependent diabetes mellitus) is an autoimmune disorder developing when insulin-producing cells of the pancreas in the body have been destroyed and the pancreas produces little or no insulin." (PMID 32872226, 2020). "With regard to composite mortality or major complication, both patients with diabetes (OR=1.79; 95% CI 1.36 - 2.35; P<0.001) and without it (OR=1.39; 95% CI 1.10-1.75; P=0.006) had higher unadjusted rates if they had received postoperative insulin." (PMID 33118731, 2020). "Furthermore, among adults without diabetes, heart rate variability is lower in adults with elevated insulin levels." (PMID 32393179, 2020). "Moreover, women who had received insulin treatment for GDM developed diabetes earlier, and only a few women (1.2%) without insulin treatment developed type 1 diabetes." (PMID 32725280, 2020). "Third, we did not balance the length of time with diabetes and insulin versus non-insulin." (PMID 32899821, 2020). "Indeed, it was recently reported that in addition to terminal UPR signaling, imatinib also directly affects insulin secretion from beta cells and promotes reactive oxygen species (ROS) scavenging by B cells in NOD mice, an effect which is essential for diabetes reversal." (PMID 33339173, 2020). "In this study, we investigated which metabolites measured by a GC–MS assay are associated with early indices of disturbances in glucose metabolism and insulin sensitivity in individuals that do not use glucose lowering drugs and do not have a history of diabetes mellitus." (PMID 32124065, 2020). "However, a small study from Kumasi, Ghana (n = 120) reported that 18% of patients with insulin‐dependent diabetes, 9% of patients with non‐insulin–requiring diabetes, and 2% of individuals without diabetes were positive for GAD65Ab." (PMID 32378803, 2020).
diabetes (continued). "Consistently, mice lacking p38δ present elevated insulin levels and are protected against diabetes." (PMID 32872540, 2020). "3P-MACE HRs were significantly in favor of GLP-1RA irrespectively of sex, in those aged 65 years or older, with longer diabetes duration, not treated with long-acting insulin, not treated with sulfonylureas, treated with ACE inhibitors, but irrespectively of statin treatment." (PMID 32522260, 2020). "Diabetic Mellitus is a non-communicable heterogeneous group of metabolic disorders with elevated blood glucose and abnormally shifted carbohydrate, fat and protein metabolism resulting from defects in insulin secretion and/or insulin action." (PMID 32822414, 2020). "Although insulin therapy is a common treatment for diabetes, it is not a cure." (PMID 32824212, 2020). "Although the involvement of this gene in diabetes and insulin secretion has not been reported, Tcerg1 might indirectly affect insulin secretion through the regulation of insulin secretion related gene expression." (PMID 32502168, 2020). "Fourth, we did not distinguish incident diabetes in terms of type, but the incidence of type 1 diabetes was very low, fasting glucose was only mildly elevated, and insulin levels were high-normal among the participants; accordingly, these participants are unlikely to develop type 1 diabetes." (PMID 33302966, 2020). "At Clinic C, which was without a diabetes team, the clinic manager noted that diabetes leadership is low in the clinic and this might lead to ineffective implementation of the insulin PDA." (PMID 33378349, 2020). "Considering that most diabetic patients may control their blood glucose with hypoglycemic drugs or insulin, we hypothesize that it is the blood glucose level rather than the diabetes that is involved in the development of PGS." (PMID 32509882, 2020). "Diabetes mellitus (DM) is a disorder of the metabolism of carbohydrates, proteins, and lipids, and its principal characteristic is hyperglycemia due to lower secretion or lack of insulin." (PMID 32423173, 2020). "We focused on diabetes, showing that R-Tf-D-LP4 peptide treatment of STZ/HFD-32 fed mice restored the elevated blood glucose back to close to normal levels, and increased the number and average size of islets and their insulin content as compared to untreated controls." (PMID 32093016, 2020). "We validated our results for the identified metabolites in an independent subset of the NEO cohort in individuals without diagnosis of diabetes mellitus that did not use glucose lowering medication using the same indices of glucose metabolism and insulin sensitivity." (PMID 32124065, 2020). "Even though ghrelin treatment did not prevent nor delay the onset of diabetes mellitus in the pre-diabetic, ghrelin-treated group, ghrelin probably increases serum insulin level via the direct stimulation of insulin and enhancement of the proliferation of pancreatic beta cells." (PMID 32325912, 2020). "In this study, basal insulin secretion was not correlated with ucOC in diabetes." (PMID 32821293, 2020). "However, in individuals with diabetes and impaired glucose tolerance, the correlation between fasting insulin and insulin resistance is as strong as individuals with normal glucose tolerance." (PMID 32957570, 2020). "Insulin or AGE inhibitor aminoguanidine could reverse the decreased OCT2/3 by diabetes, inferring that the accumulation of AGEs may be involved in impaired expression of renal OCTs by diabetes." (PMID 32290519, 2020). "Importantly, not all patients with diabetes experience severe hypoglycaemia and 80% of patients with T2D and 60% of patients with T1D seem protected even after 5 years of insulin therapy (UK Hypoglycaemia Study." (PMID 32716554, 2020). "Furthermore, most patients often present hypoglycemia after insulin treatment, with no beneficial effects on diabetes-related cardiovascular complications." (PMID 32392536, 2020).
diabetes (continued). "Furthermore, diabetes-induced activation of protein kinase-β (PKC-β) increases production of AGE from the polyol pathway and leads to accelerated atherosclerosis, reduced insulin-stimulated eNOS production and increased expression of the vasoconstrictive molecule, ET-1." (PMID 32816039, 2020). "It is reported that patients with type 2 diabetes mellitus complicated with nonalcoholic fatty liver disease (NFALD) were treated with aggliptin for 12 months, and the scores of nonalcoholic fatty hepatitis (NASH), ferritin, insulin and collagen IV 7S were significantly improved." (PMID 32368255, 2020). "Although diabetes induced by rapid depletion of insulin with use of streptozotocin promotes thinning of the inner retina as early as 2 months after diabetes induction, no apparent changes in retinal thickness were observed in animals fed high fat diet up to 12 months." (PMID 31979105, 2020). "While the reasons for uncontrolled DM are complex and multifactorial, one study found that insulin refusal, lack of insulin titration, lack of knowledge of diabetes, side effects and infrequent clinic attendance were some of more common contributors to uncontrolled DM." (PMID 32957991, 2020). "Finally, we did not perform routine insulin measuements, given that only two patients included had diabetes mellitus." (PMID 33076877, 2020). "Moreover, in 118 participants without diabetes, who underwent an intravenous glucose tolerance test, AHI was independently associated with insulin sensitivity, even after adjusting for age, sex, race, and body fat percentage." (PMID 32562183, 2020). "However, non-glucose/insulin related reliable and validated biomarkers are needed to complement our knowledge on diabetes development and indicate prognostic biomarkers." (PMID 32708684, 2020). "In addition, diabetes duration [12 (SD 7.7) vs. 6.6 years (SD 6.6)] and HbA1c [60 mmol/mol (SD 11) vs. 54 mmol/mol (SD 9)] was higher in the exogenous insulin-treated patients than in the non-insulin treated patients (p < 0.05)." (PMID 32903679, 2020). "However, the catastrophic health cost for families whose children have diabetes make it necessary for health care advocates to make insulin availability a priority so as not to drive these families into the impoverishing level because of the disease." (PMID 32874425, 2020). "This is consistent with an early observation of localized diabetes within the brain, which noted that, in the absence of systemic symptoms of diabetes, insulin and IGF-1 resistance were detectable in the hippocampus and, to a lesser extent, the cerebellar cortex." (PMID 32226608, 2020). "Given its prominence in the single cell, as well as multicellular (tissue), repair pathways, it is not surprising that impaired insulin signaling leads to major wound repair defects in diseases such as diabetes where chronic wounds are symptomatically observed." (PMID 33306674, 2020). "Finally, 11 patients (4.6%) mentioned that they had been prescribed neither insulin nor pills for their diabetes." (PMID 33083495, 2020). "Case 9 was notable as they did not have a history of diabetes mellitus (HbA1c 5.6% or 38 mmol/mol) and was treated in a ward setting using fixed-rate intravenous insulin of 2 units/h (0.02 units/kg/h) administered concurrently with intravenous 4% dextrose + n/5 saline at 80 mL/h." (PMID 33291273, 2020). "It was originally thought that some anti-diabetes treatment (such as metformin, PPARs, DPP4 inhibitors, GLP-1R agonists, SGLT2 inhibitors and insulin therapy) could influence the course of COVID-19; however, no convincing evidence has emerged to support this view." (PMID 33335527, 2020). "However, the insulin requirement level was controlled by physicians and returned to normal at discharge time and there were no adverse events according to uncontrolled diabetes in patients." (PMID 32943404, 2020).